ELOVL5 (ELOVL fatty acid elongase 5)
Description:
Catalyzes the first and rate-limiting reaction of the four reactions that constitute the long-chain fatty acids elongation cycle. This endoplasmic reticulum-bound enzymatic process allows the addition of 2 carbons to the chain of long- and very long-chain fatty acids (VLCFAs) per cycle. Condensing enzyme that acts specifically toward polyunsaturated acyl-CoA with the higher activity toward C18:3(n-6) acyl-CoA. May participate in the production of monounsaturated and of polyunsaturated VLCFAs of different chain lengths that are involved in multiple biological processes as precursors of membrane lipids and lipid mediators (By similarity). In conditions where the essential linoleic and alpha linoleic fatty acids are lacking it is also involved in the synthesis of Mead acid from oleic acid (By similarity).
Synonyms: hELO1; dJ483K16.1; SCA38
Tractability: Antibody: UniProt predicts a signal peptide or a membrane-spanning region. PROTAC: ubiquitination databases record sites on it; its protein half-life has been measured.
Target class: Enzyme; Transferase
Gene: Protein-coding gene on chromosome 6 (53,260,285 to 53,349,179, reverse strand). Ensembl gene ENSG00000012660.
Subcellular location: Endoplasmic reticulum membrane; Cell projection, dendrite
Subcellular location (Human Protein Atlas): Endoplasmic reticulum
Pathways (Reactome):
Metabolism: Linoleic acid (LA) metabolism; Synthesis of very long-chain fatty acyl-CoAs; alpha-linolenic acid (ALA) metabolism
Gene expression (Transcription): MLL4 and MLL3 complexes regulate expression of PPARG target genes in adipogenesis and hepatic steatosis
Gene Ontology:
Molecular function: fatty acid elongase activity; protein binding
Biological process: fatty acid elongation, monounsaturated fatty acid; fatty acid elongation, polyunsaturated fatty acid; positive regulation of fatty acid biosynthetic process; very long-chain fatty acid biosynthetic process; alpha-linolenic acid metabolic process; fatty acid elongation, saturated fatty acid; linoleic acid metabolic process; long-chain fatty-acyl-CoA biosynthetic process; sphingolipid biosynthetic process; fatty acid biosynthetic process; fatty acid elongation; unsaturated fatty acid biosynthetic process
Cellular component: dendritic tree; endoplasmic reticulum; endoplasmic reticulum membrane; membrane; neuronal cell body; dendrite
Genetic constraint (gnomAD): Loss-of-function variants: 7 observed, 32.47 expected, observed/expected ratio (o/e) 0.22, 90% interval 0.12 to 0.41. The upper end of that interval is the gene's LOEUF score, 0.41, which puts it in group 1 of 6, group 1 being the genes least tolerant of losing a copy. Missense variants: 210 observed, 298.24 expected, observed/expected ratio (o/e) 0.7, 90% interval 0.63 to 0.79. Synonymous variants: 105 observed, 112.73 expected, observed/expected ratio (o/e) 0.93, 90% interval 0.79 to 1.1.
Homologues: Orthologues: chimpanzee ELOVL5 (100% identical), macaque ELOVL5 (99% identical), dog ELOVL5 (96% identical), mouse Elovl5 (93% identical), rat Elovl5 (93% identical), pig ELOVL5 (91% identical), guinea pig ELOVL5 (88% identical), tropical clawed frog elovl5 (77% identical), zebrafish elovl5 (70% identical), rabbit ELOVL5 (58% identical). Paralogues in human: ELOVL2 (55% identical), ELOVL4 (40% identical), ELOVL7 (34% identical), ELOVL1 (32% identical), ELOVL3 (22% identical), ELOVL6 (21% identical).
Diseases named in the same sentence as ELOVL5 in open-access papers:
ELOVL5 is named in the same sentence as 82 diseases in open-access papers, as found by Europe PMC text mining. Sharing a sentence is not in itself a finding about the gene and the disease. The quoted sentences say what the papers report.
gastric cancer (18 papers, 2020 to 2025). A primary or metastatic malignant neoplasm involving the stomach. "In gastric cancer, the mesenchymal subtype exhibits unique ferroptosis vulnerability mediated by very long-chain fatty acid protein 5 (ELOVL5) and fatty acid desaturase 1 (FADS1) dependent PUFA synthesis enhancement." (PMID 40892295, 2025). "Studies have shown that in gastric cancer cells, the expressions of long-chain fatty acid protein 5 (ELOVL5) and fatty acid desaturase 1 (FADS1) discriminate the cellular susceptibility to ferroptosis." (PMID 39170694, 2024). "In gastric cancer, it was shown that ELOVL5 and FADS1 enhance the sensitivity to ferroptosis, increasing anti-tumor effect." (PMID 38102129, 2023). "Intestinal-type gastric cancer cells fail to express ELOVL5 and FADS1 after their promoters are methylated, rendering cells resistant to ferroptosis induced via GPX4 inhibition or cysteine depletion." (PMID 37612411, 2023). "Mechanisms of how ELOVL5 activity affects cancer cells have been suggested in a few studies performed in prostate cancer, renal cell cancer, and gastric cancer cells." (PMID 36970499, 2023). "Some gastric cancer cells exhibit differential expression of ELOVL5 and FADS1 through changes in DNA methylation of their promoter regions." (PMID 36970499, 2023). "For instance, it has been demonstrated that extra-long-chain fatty acid protein 5 (ELOVL5)-mediated fatty acid elongation promotes the development of gastric cancer." (PMID 37686016, 2023). "Overexpression of ELOVL5 was also seen in prostate and gastric cancer cells for its incapability to regulate redox and mitochondrial homeostasis, and maintain appropriate production of reactive oxygen species (ROS), which pointed out a new possible pathogenetic mechanism to be studied further." (PMID 38674425, 2024). "Interestingly, previously it has been demonstrated that expression of ELOVL5 gene can affect sensitivity to ferroptosis in gastric cancer." (PMID 36714261, 2023). "Gastric cancer cells with ELOVL5-KO completely lost the ability to synthesize AA from LA." (PMID 37612411, 2023). "Gastric cancer cells with high expression of elongation of very long-chain fatty acid protein 5 (ELOVL5) and fatty acid desaturase 1 (FADS1) are more sensitive to ferroptosis, while cells that highly expressed stearoyl-CoA Desaturase 1 (SCD1) exhibit ferroptosis resistance." (PMID 34796174, 2021). "Hypermethylation of the promoter region results in low expression of ELOVL5 and FADS1 in intestinal-type gastric cancer (GC) cells, which are resistant to ferroptosis, and after supplementation with AA, the cells become ferroptosis-sensitive." (PMID 35978815, 2022). "Furthermore, elongation expression of extra-long-chain fatty acid protein 5 (ELOVL5) and fatty acid desaturase 1 (FADS1) is upregulated in mesenchymal gastric cancer cells (GCs), contributing to the development of ferroptosis." (PMID 37686016, 2023). "Although a key enzyme Elovl5 promoting ferroptosis in gastric cancer cells, was no increase in expression, another elongase Elovl7 was increased, which catalyzes the rate-limiting step in the synthesis of very long-chain fatty acids and exhibits the highest activity toward 18-carbon fatty acids." (PMID 41285716, 2025). "In particular, intestinal-type gastric cancer (GC) cells express extremely low levels of ELOVL5 and FADS1 due to hypermethylation at the promoter region and are resistant to ferroptosis, while mesenchymal-type GC cells are sensitive to ferroptosis at high levels of ELOVL5 and FADS1." (PMID 33801564, 2021).
breast carcinoma (14 papers, 2015 to 2025). "In breast cancer, ELOVL5 down-regulation is associated with increased tumor growth and metastasis through a lipid-droplet accumulation-mediated induction of TGF-β receptors." (PMID 37981715, 2023). "It was also found that a decrease in the expression of either IGFBP6 or ELOVL5 gene increases sensitivity of MDA-MB-231 breast cancer cells to LC-PUFAs and our data suggest that they cause cell death by activation of ferroptosis." (PMID 36714261, 2023). "Furthermore, low expression of Elovl5 is associated with a worse prognosis in ER+ breast cancer patients." (PMID 36056008, 2022). "A weak expression of Elovl5 is associated with a worse prognosis in breast cancer." (PMID 36056008, 2022). "Therefore, we investigated the role of Elovl5 in metastasis which remains the main risk of death in breast cancer patients." (PMID 36056008, 2022). "PUFA-specific ELOVL5 downregulation in breast cancer patients, particularly in ER + tumors, has been identified as a factor contributing to cancer proliferation and progression, with its knockdown shown to promote metastasis." (PMID 40759952, 2025). "In all, our data demonstrate that reduction in the expression of ELOVL5 or IGFBP6 genes can lead to an increase in the sensitivity of breast cancer cells to various PUFAs." (PMID 36714261, 2023). "The reason why the breast cancer cells with reduced expression of either ELOVL5 or IGFBP6 gene are more sensitive to ferroptosis is complex." (PMID 36714261, 2023). "As expected, breast cancer cells after the knockdown of either ELOVL5 or IGFBP6 gene were more sensitive to DHA (p < 0.05)." (PMID 36714261, 2023). "Next, we examined properties of breast cancer cells related to metastatic propensity after the knockdown of either ELOVL5 or IGFBP6 gene." (PMID 36714261, 2023). "The data obtained from breast cancer patients confirmed a relationship between Elovl5 expression and metastasis." (PMID 36056008, 2022). "The blockade of Elovl5-dependent elongation of fatty acids in breast cancer cells also induced an accumulation of C24:6-30:6 FA in the cellular FA fraction." (PMID 36056008, 2022). "Our results showed that the downregulation of Elovl5 expression inhibited the proliferation of breast cancer cells and reduced mammary tumor growth in murine models, which is consistent with a recent publication on prostate cancer." (PMID 36056008, 2022). "It was shown that ELOVL5 (elongase, responsible for elongation of long chain fatty acids) is upregulated in breast cancer (BC) vs. normal adjacent tissue, with the expression correlated with changes in blood lipid species." (PMID 36230586, 2022). "Although downregulation of Elovl5 expression limited breast cancer cell proliferation and cancer progression, suppression of Elovl5 promoted EMT, cell invasion and lung metastases in murine breast cancer models." (PMID 36056008, 2022). "In our study, we were able to show a decrease of Elovl5 expression by RT-qPCR as well as by IHC staining in breast cancer tissues." (PMID 36056008, 2022). "To precise the role of Elovl5 in breast cancer cell proliferation, we used mammary cell lines with different basal Elovl5 expression levels, in which we further downregulated or overexpressed Elovl5 expression." (PMID 36056008, 2022). "We evaluated the impact of LD reduction on the expression of EMT markers in breast cancer cells with Elovl5 knockdown." (PMID 36056008, 2022). "Unexpectedly, the transient or stable depletion of Elovl5 expression in the MCF-7 breast cancer cells led to the increase of the basal and maximal mitochondrial oxygen consumption." (PMID 36056008, 2022). "Given that TGFβ-R1 and TGFβ-R2 expression were upregulated in Elovl5-silenced breast cancer cells, such cancer cells should present a higher activation of downstream signaling in response to TGF-β treatment." (PMID 36056008, 2022).
breast carcinoma (continued). "We observed that transient depletion of Elovl5 in breast cancer cells using a siRNA for 48 h or its stable depletion by a shRNA in MCF-7 cells led to an intracellular accumulation of total FA and TAG." (PMID 36056008, 2022). "In conclusion, we demonstrate the role of Elovl5 in breast cancer cells through a regulation of lipid-droplet content and expression of TGF-β receptors." (PMID 36056008, 2022). "In this study, we demonstrated a role of Elovl5 in breast cancer growth and metastasis through the expression of TGF-β receptors, mediated by the storage of fat in lipid droplets." (PMID 36056008, 2022). "Overall, the analysis showed that the content of Elovl5 mRNA was significantly reduced in breast cancer tissues compared to matched normal tissues." (PMID 36056008, 2022). "The increase in the total FA and TAG content in breast cancer cells upon a depletion of Elovl5 was consistent with an activation of lipogenesis and LD formation." (PMID 36056008, 2022). "Treatments with inhibitors of DGAT1 (A922500, DGAT1i) and DGAT2 (PF-06424439, DGAT2i) activity for 48 h were able to counteract the increase of plasma membrane TGFβ-R1 and TGFβ-R2 levels in Elovl5-depleted breast cancer cells." (PMID 36056008, 2022). "To evaluate the role of Elovl5 invalidation in breast cancer progression, we crossed Elovl5 full knockout female C57BL/6 mice with MMTV-PyMT male C57BL/6 mice." (PMID 36056008, 2022). "A consequence of Elovl5 downregulation is an accumulation of LD in breast cancer cells which controlled their proliferation and invasion." (PMID 36056008, 2022). "We developed different murine breast cancer models and showed that Elovl5 controlled tumor growth and metastasis process through lipid-droplet-mediated regulation of TGF-β receptor expression." (PMID 36056008, 2022). "We confirmed at the protein level that the expression of TGF-β receptor 1 (TGFβ-R1) by immunofluorescence staining and expression of TGF-β receptor 2 (TGFβ-R2) by western blotting were enhanced in Elovl5-depleted breast cancer cells." (PMID 36056008, 2022). "Then, we analyzed Elovl5 mRNA expression in samples from 30 women with breast cancer for which we had breast tumor tissues and paired normal breast tissues." (PMID 36056008, 2022). "Here, we were interested in the elongation of very long-chain fatty acids protein 5 (Elovl5) in breast cancer." (PMID 36056008, 2022). "The effect of Elovl5 invalidation on LD content in mammary tumors was investigated, and the analysis showed more Oil Red O stained-positive cancer cells in mammary tumors of Elovl5-/- mice compared to the Elovl5−/− mice." (PMID 36056008, 2022). "The polyunsaturated fatty acid (PUFA) elongase, ELOVL5, is upregulated in breast cancer (BC) vs. adjacent normal tissue." (PMID 34439324, 2021). "Thus, the present study deepens the understanding of the contribution of the ELOVL5 gene to the regulation of ferroptosis and can be used in the development of targeted therapy for breast cancer." (PMID 41329269, 2025). "Interestingly, our previous study showed that ELOVL5 knockdown in breast cancer cells increases their sensitivity to LCPUFAs, with the observed cell death proceeding by the ferroptotic pathway." (PMID 41329269, 2025). "Thus, the reduction in the expression of ELOVL5 or IGFBP6 genes leads to increased sensitivity to the induction of ferroptosis in breast cancer cells and at the same time makes them more responsive to its inhibition." (PMID 36714261, 2023). "ELOVL5 is involved in various cancer types, including renal cancer and breast cancer." (PMID 37981715, 2023). "Moreover, the complete knockout of ELOVL5 in the mouse breast carcinoma model led to a delay in tumor development and a decrease in tumor growth." (PMID 36714261, 2023). "Thus, in this work we studied the changes in lipid metabolism in breast cancer cells with reduced expression of either ELOVL5 or IGFBP6 gene." (PMID 36714261, 2023).
breast carcinoma (continued). "Thus, we aimed to investigate the expression of TGF-β receptors in breast cancer cells upon modulation of Elovl5 expression." (PMID 36056008, 2022). "Then, we analyzed by western blotting the expression of EMT markers which showed a decrease in the expression of epithelial markers (E-cadherin and occludin) and an increased expression of mesenchymal markers (vimentin and N-cadherin) in Elovl5-silenced breast cancer cells." (PMID 36056008, 2022). "Thus, we indicated that Elovl5-depleted breast cancer cells increased their mitochondrial oxygen consumption and contained more acetyl-CoA while the abrogation of LD formation by DGAT inhibitors deprived acetyl-CoA levels." (PMID 36056008, 2022). "In this study, we were interested in the role of Elovl5 in breast cancer progression." (PMID 36056008, 2022). "Moreover, treatment with the inhibitors of TGF-β receptors (LY2157299 and LY2109761) alleviated the repression of proliferation induced by Elovl5 silencing in breast cancer cells." (PMID 36056008, 2022). "Thus, it is not surprising to observe an induction of the mitochondrial oxygen consumption in Elovl5-silenced breast cancer cells." (PMID 36056008, 2022). "Interestingly, we demonstrated that the formation of metastases and metastasis-associated features (cell invasion, TGF-β receptor expression and EMT) in breast cancer models were promoted by dampening Elovl5 expression." (PMID 36056008, 2022). "Of note, Elovl5 expression in patients with an N0 status is already much lower in Her2+ and TNBC breast cancer tissues compared to ER+ breast cancer tissues and is closer to the downregulated Elovl5 expression in ER+ breast cancer tissues from patients with N1 status." (PMID 36056008, 2022). "We observed that breast cancer tumors had a lower expression of Elovl5 than normal breast tissues." (PMID 36056008, 2022). "Indeed, METABRIC dataset showed that ER+ breast cancer expressed higher Elovl5 mRNA levels than Her2+ and TNBC." (PMID 36056008, 2022). "From the METABRIC dataset, we found that a lower expression of Elovl5 mRNA is associated with a shorter overall survival (OS) time for breast cancer patients without distinction of subtypes." (PMID 36056008, 2022). "To confirm the association of Elovl5 expression and lymph node metastasis in breast cancer, we conducted an IHC analysis of patients with or without lymph node invasion." (PMID 36056008, 2022). "We confirmed with a H-score for the IHC Elovl5 staining that the average expression of Elovl5 was downregulated in breast cancer (T) tissue compared to adjacent normal (NT) breast tissue and was higher in ER+ breast cancer samples than in ER− breast cancer tissues (Her2+ and TNBC)." (PMID 36056008, 2022). "This work suggests that treatment with DGAT inhibitors could block LD formation and the subsequent TGF-β signaling through repression of TGF-β receptor expression in Elovl5-depleted breast cancer cells." (PMID 36056008, 2022). "Altogether these data show that Elovl5 controlled proliferation and tumor growth in breast cancer." (PMID 36056008, 2022). "Furthermore, we clearly confirmed that ablation of Elovl5 expression with siRNA or shRNA in breast cancer cells inhibited cell proliferation and promoted cell invasion." (PMID 36056008, 2022). "We also found that Elovl5 mRNA was differently expressed between the subtypes of breast cancer." (PMID 36056008, 2022). "Thus, the obtained data indicate that malignant breast tumors with reduced expression of the ELOVL5 and IGFBP6 genes can metastasize with a higher probability due to a more efficient invasion of tumor cells." (PMID 34149804, 2021). "Analysis of spheroid formation confirmed that intercellular adhesion decreased as a result of both ELOVL5 and IGFBP6 knockdowns, thus suggesting that malignant breast tumors with reduced expression of ELOVL5 or IGFBP6 gene may metastasize more actively due to more efficient tumor cell invasion." (PMID 36714261, 2023).